PPARD (peroxisome proliferator activated receptor delta)
Diseases named in the same sentence as PPARD in open-access papers (continued):
Sharing a sentence is not in itself a finding about the gene and the disease.
Insulin resistance (continued). "Pharmacological evidence indicates that PPARα regulates the expression of genes involved in lipid and lipoprotein homeostasis, while PPARδ plays a key role in lipid metabolism and insulin resistance." (PMID 34502131, 2021). "Fatty acid metabolism is regulated by the peroxisome proliferator-activated receptor delta (PPAR-δ) gene, which has a certain role in insulin resistance; hence therapy with Vitamin D decreases insulin resistance." (PMID 34567869, 2021). "These identified functions of PPARδ activation provide a number of therapeutic targets for improving insulin resistance and oxidative stress mediated by alcohol consumption." (PMID 32760285, 2020). "Herein, we investigated the effects of METRNL on lipid-mediated inflammation and insulin resistance in skeletal muscle via AMP-activated protein kinase (AMPK) or peroxisome proliferator-activated receptor δ (PPARδ)." (PMID 30213948, 2018). "In conclusion, the current study is the first to show that METRNL ameliorates lipid-induced inflammation and insulin resistance via AMPK- or PPARδ-dependent signaling in skeletal muscle of mice." (PMID 30213948, 2018). "The nuclear receptors peroxisome proliferator-activated receptor γ (PPARγ) and peroxisome proliferator-activated receptor δ (PPARδ) play central roles in regulating metabolism in adipose tissue, as well as being targets for the treatment of insulin resistance." (PMID 21843327, 2011). "BCAAs have also been causally implicated in the pathogenesis of insulin resistance, indicating that one possible mechanism by which PPARδ improves insulin resistance is by reducing the concentration of BCAAs." (PMID 21843327, 2011). "The main aim of this review is to highlight the central role for activated PPARδ in the reversal of any tendency toward the development of insulin resistance." (PMID 18815630, 2008). "In addition, METRNL has been reported to attenuate lipid-induced inflammation and insulin resistance via AMPK- or PPARδ-dependent pathways in skeletal muscle of mice." (PMID 38914997, 2024). "Furthermore, PPARδ was identified as a downstream target of miR-29a, and treatment with GW501516, a PPARδ agonist, partially mitigated insulin resistance induced by miR-29a." (PMID 39327610, 2024). "There may be a link between PPARδ and GLP-1R in the diabetic condition, which may be the molecular mechanism by which PPARD gene variants influence T2DM risk, insulin resistance and clinical response to exenatide." (PMID 36051387, 2022). "PPARδ activation markedly improves glucose tolerance and insulin resistance." (PMID 34502131, 2021). "PPARD and NOS1AP are directly or indirectly involved in the regulation of β-cell function and insulin resistance, which suggests that genetic polymorphisms in the two genes may contribute to interindividual differences in nateglinide response." (PMID 34772419, 2021). "A previous study reported that METRNL could alleviate lipid‐induced inflammation and insulin resistance via AMPK or PPARδ‐dependent pathways." (PMID 31859449, 2020). "Given the important roles of FFA in the genesis of type 2 diabetes, the enhanced fatty acid oxidation as well as the upregulation of the oxidative phosphorylation pathway by PPARD may be beneficial in alleviation of insulin resistance and adiposity." (PMID 24288525, 2013). "In addition, we provide evidence for a role of PPARδ in regulating muscle insulin resistance, as indicated by the glucose tolerance test results." (PMID 22040534, 2011). "Similarly, in the case of ob/ob mice, PPARδ activation markedly improvedglucose tolerance and insulin resistance." (PMID 18566690, 2008). "The continuous down-regulation of Pparδ in the middle part of the small intestine might also be related to development of insulin resistance, as Pparδ null mice become more glucose intolerant on a high-fat diet." (PMID 18457598, 2008).
Insulin resistance (continued). "The ability of PPARδ to stimulate mitochondrial biogenesis and oxidative function suggests that PPARδ could be important for control of insulin resistance during normal aging." (PMID 15328533, 2004). "Therefore, our findings suggest that PPARD rs2016520 may affect the biological function of PPARδ, thereby influenceing the therapeutic effects of exenatide on improving insulin resistance of patients with T2DM." (PMID 36051387, 2022). "Therefore, the PPARD risk mutations may serve as exenatide response predictors based on PPARδ regulating GLP-1R expression and mediating insulin resistance." (PMID 36051387, 2022). "It was therefore suggested, that PPARβ/δ controls the hepatic energy substrate homeostasis by coordinated regulation of glucose and fatty acid metabolism, which provides a molecular basis for developing PPARδ agonists in order to manage hyperglycemia and insulin resistance." (PMID 31121839, 2019). "Therefore, by activating PPARα, PPARδ, and PPARγ together and reducing TG in skeletal muscles, bezafibrate might improve glucose intolerance and insulin resistance in skeletal muscle." (PMID 25360162, 2014). "1,25(OH)2D additionally activates the transcription factor peroxisome proliferator-activated receptor delta (PPAR-δ), which mobilizes fatty acids in skeletal muscle and, thus, reduces free fatty acid (FFA)-induced insulin resistance." (PMID 35206632, 2022). "Taken together, the study shows PPARδ enhances fatty acid utilization and uncoupled respiration via UCP3 and protects against EtOH-induced lipotoxicity and insulin resistance in skeletal muscle." (PMID 32760285, 2020). "siRNA-mediated suppression of AMPK and PPARδ abrogated the suppressive effects of METRNL on palmitate-induced inflammation and insulin resistance." (PMID 30213948, 2018). "In the current study, we report for the first time that METRNL alleviates inflammation and insulin resistance and induces fatty acid oxidation through AMPK or PPARδ-dependent signaling in skeletal muscle." (PMID 30213948, 2018). "siRNA targeting PPARδ markedly blocked the effects of METRNL on palmitate-induced inflammation and insulin resistance, demonstrating that METRNL ameliorates palmitate-induced inflammation and insulin resistance through PPARδ-dependent signaling." (PMID 30213948, 2018). "Regarding the mechanism of how PPARδ ameliorates cardiac fibrosis, a previous study indicated that the PPARβ/δ agonist inhibited STAT3 activation and insulin resistance in human liver cells." (PMID 27519769, 2016). "In recent years, selective PPARδ agonists, such as synthetic GW501516, have been shown to suppress body weight increase and reduce insulin resistance in obese diabetic mice." (PMID 21799697, 2011). "Moreover, we also observed the critical role of PPARδ in regulation of the expression of GLP-1R, the receptor for exenatide, and effects on insulin resistance." (PMID 36051387, 2022). "Therefore, using a PPARδ specific ligand, GW0742, can activate the protective effects from hypertriglyceridemia and insulin resistance as what PPARα and PPARγ do but alternatively prevents the sequel of edema and fluid retention induced by PPARγ." (PMID 27519769, 2016). "They found that telmisartan treatment could reverse high-fat diet-induced insulin resistance and glucose intolerance in WT but not in muscle-specific PPARδ knockout mice." (PMID 31073415, 2019). "AMPK siRNA or PPARδ markedly mitigated the inhibitory effects on palmitate-induced inflammation and insulin resistance, indicating that METRNL-induced AMPK and PPARδ could contribute to the amelioration of inflammation and insulin resistance." (PMID 30213948, 2018).
diabetes (71 papers, 2005 to 2026). "Together, our data provide novel insight into the mechanistic basis underlying diabetes-tuberculosis comorbidity and shed light on PPARδ as a potential target for therapeutic intervention." (PMID 38989454, 2024). "Comparison of genotype and frequencies of PPARD variants between healthy controls (n = 200) and patients with type 2 diabetes mellitus (T2DM) (n = 300)." (PMID 36051387, 2022). "Moreover, PPARδ has been shown to protect vascular endothelial cells and mitigate lipid imbalance associated with diabetes by regulating HO-1." (PMID 39856769, 2025). "PPARD is a promising drug target for heart defects caused by diabetes." (PMID 26697060, 2015). "Thus, change of PPARδ expression seems associated with the progress of diabetes and the higher mortality rate after SCI." (PMID 24817882, 2014). "PPARδ activation and/or overexpression, improving increasedglucose use in diabetic heart, shows promises as a therapeutic strategy forcardiac dysfunction caused by diabetes and ischemia." (PMID 19325917, 2009). "PPARδ activation has been demonstrated to alleviate oxidative stress and endothelial dysfunction in diabetes." (PMID 39856769, 2025). "Our findings from western blot and DHE staining indicated that the protective effect of CA on diabetes-related vascular injury and oxidative stress lies in its activation of Nrf2/HO-1 pathway and PPARδ." (PMID 39856769, 2025). "Our findings corroborated previous observations, revealing higher PPARδ gene expression in patients with diabetes, which was further amplified upon HKMT stimulation." (PMID 38989454, 2024). "To further understand the role of PPARδ in the pathophysiology of TB in the setting of diabetes, we first examined its expression in monocytic cells isolated from lean controls without diabetes, as well as OB individuals with or without diabetes." (PMID 38989454, 2024). "Secondly, our previous work identified PPARδ as a potential therapeutic target for improving synaptic plasticity in rodent models of diabetes/AD." (PMID 37190025, 2023). "The baseline characteristics in type 2 diabetes mellitus (T2DM) patients with various PPARD rs3777744 genotypes before treatment with exenatide (n=300)." (PMID 36051387, 2022). "The baseline characteristics in type 2 diabetes mellitus (T2DM) patients with various PPARD rs2016520 genotypes before treatment with exenatide (n=300)." (PMID 36051387, 2022). "The direct Wnt/β‐catenin signalling target genes, such as transcription factor 7 like 2 (TCF7L2), wnt1‐induced secreted protein 1 (WISP1), GLP1 and peroxisome proliferator‐activated receptor delta (PPARδ), play major roles in obesity and diabetes." (PMID 35384342, 2022). "This study was designed to investigate a potential association of PPARD rs2016520 (T/C) and NOS1AP rs12742393 (A/C) polymorphisms with efficacy of nateglinide in newly diagnosed Chinese patients with type 2 diabetes mellitus (T2DM)." (PMID 34772419, 2021). "Polymorphisms of PPARD and PPARG are associated with risk and prognosis of many diseases, including cardiovascular disease, diabetes, brain diseases, medulloblastoma and other cancers." (PMID 32198386, 2020). "In this study, we aimed to investigate the regulatory role of PPARδ in diabetes-induced cardiac fibrosis under telmisartan treatment." (PMID 27519769, 2016). "A recent study has shown that PPARD induces glucose transport to the heart muscle cells and that diabetes patients have decreased PPARD expression in cardiac muscle when glycemic levels are high." (PMID 26697060, 2015). "Likewise, exercise is known to activate AMPK and is found to ameliorate ER stress and endothelial dysfunction in diabetes through PPARδ." (PMID 34439415, 2021). "Taken together, diabetes leads to the impairment of mitochondrial biogenesis that may be caused by the downregulation of PGC-1α and/or PPARδ, resulting in reduced oxidative capacity in skeletal muscle." (PMID 29036909, 2017).
diabetes (continued). "In addition, the survival times in two-week induction diabetes were longer than those in eight-week induction group, which is consistent with the expression of PPARδ in the spinal cord." (PMID 24817882, 2014). "Thus, change of PPARδ expression with the progress of diabetes seems responsible for the higher mortality rate after SCI." (PMID 24817882, 2014). "PPARδ agonists might form effective drugs forobesity, diabetes, and cardiovascular disease." (PMID 18584037, 2008). "Additionally, while our findings suggest a potential therapeutic role for PPARδ antagonists in mitigating inflammation, further preclinical and clinical investigations are warranted to elucidate the efficacy and safety of such interventions in TB patients, especially those with concomitant diabetes." (PMID 38989454, 2024). "A decrease in PPARδ expression was observed in spinal cords of STZ-diabetic rats, and this change was more marked with the progress of diabetes." (PMID 24817882, 2014). "However, the relationship between the progress of diabetes and PPARδ in SCI remains unknown." (PMID 24817882, 2014). "In parallel, we observed a strong association between PPARδ and markers of worsened glucose homeostasis seen in the elevation of HOMA-IR and HbA1C levels in individuals with diabetes compared to those without." (PMID 38989454, 2024). "We compared the expression of PPARδ in lean patients without diabetes (non-diabetes: ND Lean), obese patients without diabetes (ND OB), and obese patients with diabetes (D OB)." (PMID 38989454, 2024). "Intriguingly, correlation analysis showed a significant association between PPARδ, but not CD36, and CCL2, therein implicating subclinical inflammatory potentiation of monocytic cells in patients with diabetes." (PMID 38989454, 2024). "In the present study, PPARδ expression in the spinal cord was compared between normal and STZ-diabetic rats to indicate that diabetes reduced PPARδ expression in the spinal cords of rats and is associated with STZ-induced hyperglycemia and systemic inflammation." (PMID 24817882, 2014). "Additionally, using peripheral blood mononuclear cells (PBMCs) from patients with or without diabetes, we show that pharmacological inhibition of PPARδ, but not CD36, mitigates HKMT-induced inflammatory responses." (PMID 38989454, 2024). "The impact of PPARδ upregulation was further manifested by a significant increase in cell foaming, as evidenced by elevated PLIN2 protein expression in patients with diabetes compared to those without." (PMID 38989454, 2024). "We then isolated PBMCs from individuals with or without diabetes and pretreated them with either SSO to inhibit CD36 or GSK3787 to inhibit PPARδ before exposing them to HKMT." (PMID 38989454, 2024). "Remarkably, the inhibition of PPARδ using GSK3787 significantly reduced its gene expression compared with HKMT stimulation alone in samples from both patients with and without diabetes." (PMID 38989454, 2024). "Importantly, we showed elevated gene expression of PPARδ, CD36, and CCL2 in monocytic cells from OB individuals with diabetes compared with those without." (PMID 38989454, 2024).
colon carcinoma (59 papers, 2005 to 2025). "Further, three somatic PPARD variants, c.425-9C>T, c.548A>G (p.Y183C), and c.628-16G>A, were detected in three sporadic colon tumors (group I)." (PMID 24391853, 2013). "In a murine xenograft cancer model, the disruption of both PPARδ alleles in human HCT-116 colon carcinoma cellsdecreased tumorigenicity, suggesting that activation of PPARδ promotestumor growth." (PMID 18551185, 2008). "In addition, the clinical observations showed that both HBXIP and PPARδ were highly expressed in colonic carcinoma, and HBXIP expression was positively associated with that of PPARδ in the clinical specimen." (PMID 29416623, 2018). "Then we wondered whether the expression of HBXIP was associated with that of PPARδ in the colonic cancer cells." (PMID 29416623, 2018). "PPARδ deficiency disrupts hypoxia-mediated tumorigenic potential of colonic cancer cells." (PMID 29416623, 2018). "Furthermore, we found that PPARδ expression was tightly associated with highly malignant morphology of colon cancer cells." (PMID 16969348, 2006). "Thus, we wondered whether the expression of HBXIP was associated with that of PPARδ in the clinical colonic cancer patients." (PMID 29416623, 2018). "Beyond this, AMPK-induced PPARδ-S50 phosphorylation inhibits colon cancer growth and metastasis by suppressing the transcriptional activity of PPARδ." (PMID 39875357, 2025). "Studies have demonstrated that PPARδ can promote colon cancer proliferation and migration, whereas PPARα and PPARγ retard colon cancer progression." (PMID 40675969, 2025). "PPARδ promoted the proliferation and migration of colon cancer cells by increasing NKD1 transcription." (PMID 40675969, 2025). "For instance, PPARD knockdown promoted proliferation and resistance to treatment in vitro in the established colon cancer cell line KM12C." (PMID 41148824, 2025). "PPARδ overexpression with NKD1 gene knockdown markedly impeded the migration of colon cancer cells, indicating that PPARδ enhances colon cancer cell migration via NKD1." (PMID 40675969, 2025). "Functionally, the PPARδ/NKD1/MYC signaling pathway increased colon cancer cells’ proliferation, migration and angiogenesis capabilities." (PMID 40675969, 2025). "Although several studies showed that PPARδ is protumorigenic, protective effects of PPARδ were also reported, suggesting a complex and diverse role of PPARδ in colon cancer." (PMID 36162507, 2022). "The latest research pointed out that PPARδ promoted liver metastasis of colon cancer by inducing the expansion of colonic stem cells." (PMID 35151320, 2022). "In colon cancer, it was revealed that the expression of PPARδ in human colon cancer tissues was significantly higher than that of adenoma polyps and normal intestinal mucosa." (PMID 35151320, 2022). "Collectively, our data indicate that fatty acids stimulate CPT1A expression to enhance FAO and Wnt signaling mainly through PPARδ activation in colon cancer cells." (PMID 32913185, 2020). "For example, indomethacin has been shown to promote the apoptosis of colon cancer cells by inhibiting peroxisome proliferator-activated receptor δ (PPARδ) activity." (PMID 31693710, 2019). "Conversely, the expression of PPARδ was remarkably reduced when HBXIP was knockdown by transiently transfecting HBXIP siRNA (si-HBXIP) in colonic cancer SW480 or HT-29 cells respectively." (PMID 29416623, 2018). "In function, MTT, EdU and colony formation data demonstrated that HBXIP enhanced the proliferation of colonic cancer cells in PPARδ-dependent manner." (PMID 29416623, 2018). "Intriguingly, we observed that the mRNA and protein levels of PPARδ were significantly elevated by transiently transfecting HBXIP expression plasmids (pCMV-HBXIP) in colonic cancer SW480 and HT-29 cells." (PMID 29416623, 2018). "Taken together, these data strongly suggest that HBXIP promoted the proliferation of colonic cancer cells via activating PPARδ." (PMID 29416623, 2018).